CNP (2',3'-cyclic nucleotide 3' phosphodiesterase)
Diseases named in the same sentence as CNP in open-access papers (continued):
Sharing a sentence is not in itself a finding about the gene and the disease.
spinal cord trauma (1 paper, 2023). "Data from the T + SCI group indicate that the endurance training before spinal cord trauma affected the correlation between the levels of immature CNP-ase oligodendrocytes and the recovery of motor activity." (PMID 37239968, 2023).
vitamin D deficiency (1 paper, 2024). A nutritional condition produced by a deficiency of VITAMIN D in the diet, insufficient production of vitamin D in the skin, inadequate absorption of vitamin D from the diet, or abnormal conversion of vitamin D to its bioactive metabolites. "The risk of vitamin D deficiency decreased with increasing exposure to BP3, TRS, CNP, and MC1." (PMID 38732537, 2024).
tumor (20 papers, 2014 to 2026). "Immunofluorescence staining further confirmed that cNP or cNP combined with anti-PD-1 therapy effectively reduced NET-DNA deposition in tumor tissue." (PMID 42099381, 2026). "More importantly, by blocking the recruitment of monocytes to tumor tissue, CNP/siCCR2 can reprogram the tumor microenvironment, suppress tumor growth, reduce tumor metastasis, and exert effective anti-tumor effects." (PMID 38338674, 2024). "Of note, in our models, the mesenchymal signature drove a faster tumor progression as compared to CNP, as evidenced by the difference in mice survival (M1, 29 days; M2, 27 days; CNP1, 54 days)." (PMID 32789014, 2020). "Additionally, CnP combined with gemcitabine inhibited tumor growth and the desmoplasia process, which shows the potential of developing CnP as an adjuvant antitumor drug." (PMID 35327514, 2022). "It was published that tumor cells exhibit higher ROS levels than normal (healthy) cells and that CNP may exhibit prooxidative as well as antioxidative properties." (PMID 31951630, 2020). "Furthermore, we observed CNP-induced changes in mitochondrial bioenergetics, dynamics, and cristae morphology demonstrating mitochondrial dysfunction which finally led to tumor cell death." (PMID 31951630, 2020). "As the viability of cells is dependent on proper mitochondrial function, and MitoSOX staining hints to a higher superoxide (O2.-) level in tumor cell mitochondria vs normal cell mitochondria, the results thus far indicate a pivotal role of mitochondria in the selective toxicity of CNP." (PMID 31951630, 2020). "In hepatocellular carcinoma, CnP inhibits the expression of α-SMA, the activation marker of CAFs, and the tumor-promoting cytokine production such as IL-6, IL-8, and CCL-2 of CAFs." (PMID 35327514, 2022). "Interestingly, CNP at concentrations of 150–300 μM show on one hand a selective antioxidative property in normal (healthy) cells protecting these cells against oxidative impacts such as paraquat or hydrogen peroxide, and on the other hand CNP show a prooxidative cytotoxic activity in tumor cells." (PMID 31951630, 2020). "For comparing the groups of TNP-PMS/SOR and CNP-PMS/SOR, it was observed that obviously larger amount of nanoparticles is accumulated at tumor tissues by injection with TNP-PMS/SOR than the CNP-PMS/SOR." (PMID 31735093, 2019). "Tumour-bearing mice were sorted into groups (n = 6) and injected with 5 mg/kg DTX, 3 mg/kg FTY, 5 mg/kg DTX + 3 mg/kg FTY, empty CNP, CNP1 (5 mg/kg DTX + 3 mg/kg FTY), CNP2 (2 mg/kg DTX + 2 mg/kg FTY)." (PMID 28695300, 2017). "We detected no consistent difference in cell proliferation, expression of epithelial or fibroblast lineage markers, nor indeed in the expression of WT1, in size-matched tumours from Cre-induced CNP mice with or without exposure to asbestos." (PMID 37441092, 2023). "In addition, SOX10+ cells were lowly proliferative, progressed to a CNP+/CC1+/MBP− immature pre-oligodendrocyte state and were restricted to MBP+ tumour regions." (PMID 33846316, 2021). "These CNP being non-toxic for stromal cells show a cytotoxic and anti-invasive effect on tumor cells, indicating a bifunctional role of CNP in tumor–stroma interaction." (PMID 25479549, 2015). "CB839 treatment did not affect the survival of CNP tumor-bearing mice." (PMID 32789014, 2020). "However, a recent study with extensive gene expression profiling both at the whole tumor level and individual tumor cells highlights 2 main tumor-intrinsic transcriptional subtypes, the mesenchymal and the non-mesenchymal (defined in our study as CNP, for classical, neural, and proneural)." (PMID 32789014, 2020).
tumor (continued). "Interestingly, the distribution of drugs at tumor sites was significantly different in various groups after 6 h of injection, with the CTNP-PMS/SOR resulted in the most amount of drugs were detected at tumor tissues and then followed by TNP-PMS/SOR, CNP-PMS/SOR, and CNP-PMS/SOR." (PMID 31735093, 2019). "SOX10+ tumour cells were significantly less proliferative than tumour cells that remained SOX10- within the same region and occasionally expressed the immature oligodendrocyte markers CNP and CC1, but were again negative for the mature marker MBP." (PMID 33846316, 2021).
cancer (7 papers, 2016 to 2025). A tumor composed of atypical neoplastic, often pleomorphic cells that invade other tissues. "Elevated ROS levels and accordingly altered redox-status makes the cancer cell more vulnerable, thus providing an excellent tool for therapeutic treatment with prooxidant CNP." (PMID 31951630, 2020). "This indicates that the SOD-mimetic activity of CNP does not only lead to a decrease in cancer cell viability but also induces a mitochondrial dysfunction." (PMID 31951630, 2020). "Sildenafil synergistically potentiated the effects of CNP on cell proliferation and ERK phosphorylation in RMS, indicating that cGMP is a negative regulator of cell proliferation and ERK phosphorylation in this cancer." (PMID 26816265, 2016). "Finally, CNP-1F and CNP-2A have been shown to exhibit no cytotoxic effects when assessing cell viability in both a human cancer cell line (HeLa) and a healthy human cell line (EA.hy926), making them suitable for use in biomedical applications." (PMID 36679262, 2023).
neurological diseases (7 papers, 2019 to 2025). "A previous report attributes a canine adult-onset, slowly progressive neurologic disease to a homozygous CNP single base deletion frame-shift variant." (PMID 38397235, 2024). "This variant was recognized as a plausible causal candidate because a different homozygous CNP variant was known to cause a similar neurological disease of Dalmatian dogs that was also characterized by autofluorescent storage body accumulation and myelin abnormalities." (PMID 38397235, 2024). "As a label-free modality, it is applicable to most vertebrates, i.e., not limited to fluorescently-labeled transgenic mice, thus simplifying experimental designs for studying neurological disorders in models where OL markers, such as CNP and myelin-associated glycoprotein (MAG), are dysregulated." (PMID 31293394, 2019).
infection (6 papers, 2014 to 2024). The state of being infected such as from the introduction of a foreign agent such as serum, vaccine, antigenic substance or organism. "If however CNP is targeting a different process in the mitochondria then the addition of Cyclosporin A before infection will additively or synergistically lead to an increased inhibition of SARS-CoV-2 replication." (PMID 38117830, 2023). "Our mouse data shows that pre-treatment with CNP inhibited SARS-CoV-2 infection to below detectable levels in lungs throughout the course of infection." (PMID 38117830, 2023). "Accordingly, we found that at Hour 1 after infection, the amount of cNP in apoptotic cells was 9.4-fold higher than that in non-apoptotic cells on a per cell basis." (PMID 35733972, 2022). "Moreover, we observed that GZ01 infection also led to the decrease of OPC (Olig1+) and immature oligodendrocytes (CNP+)." (PMID 30083387, 2018). "At 6-hours post-infection (hpi), we confirmed that gRNA levels are not significantly different between CNP stable cells and GFP stable cells and, further show that sgRNA levels are not altered by CNP." (PMID 38117830, 2023).
cardiovascular diseases (4 papers, 2016 to 2025). "Given that cardiovascular diseases may affect the treatment outcome of NSCLC, we speculate that the expression of GST and CNP could potentially serve as markers for the diagnosis of atherosclerotic complications in NSCLC patients." (PMID 34308964, 2021).
heart diseases (4 papers, 2018 to 2024). "One very consistent finding across model systems has been a CNP‐induced enhancement of diastolic function in both health and cardiac disease." (PMID 37493451, 2023). "Our hypothesis that CNP’s paracrine actions in myocardial tissues may impact plasma cGMP has not been fulfilled presumably because of the very low abundance (and faster clearance and degradation) in tissues of well people who have no history of heart disease." (PMID 38689031, 2024).
neurodegenerative disease (3 papers, 2008 to 2024). A disorder of the central nervous system characterized by gradual and progressive loss of neural tissue and neurologic function. "A 2020 report described an infantile-onset, progressive neurodegenerative disease in a male child with a homozygous CNP missense mutation identified by exome sequencing." (PMID 38397235, 2024). "The absence of immunohistochemical staining of CNPase antigen in brain sections from the proband strongly supported the homozygous CNP missense mutation as the cause of the neurodegenerative disease." (PMID 38397235, 2024).
CNP also shares sentences with these, for which no sentence is quoted: demyelinating disease (5 papers); heart failure (5); Cerebral ischemia (3); schwannoma (3); aneurysmal disease (2); demyelination (2); Down syndrome (2); epilepsy (2); infarction (2); ischemic stroke (2); lysosomal storage disease (2); neuroblastoma (2); neurofibroma (2); peripheral neuropathies (2); Sepsis (2); viral infection (2); acinar carcinoma (1); adenocarcinoma (1); anterior ischemic optic neuropathy (1); Arthritis (1); Ataxia (1); Brain atrophy (1); brain injury (1); cardiomyopathy (1); cataract (1); chronic rhinosinusitis (1); Dystonia (1); endothelial dysfunction (1); fibrosis (1); frontotemporal dementia (1).
A further 25 diseases each share a sentence with CNP in 1 paper.